CXCL2 (C-X-C motif chemokine ligand 2)
Diseases named in the same sentence as CXCL2 in open-access papers (continued):
Sharing a sentence is not in itself a finding about the gene and the disease.
ovarian carcinoma (continued). "We showed that inhibition of IKKβ by both genetic and pharmacological means effectively reduced the transcription of CXCL1, CXCL2 and CXCL8 in GAB2-overexpressing FTSECs and ovarian cancer cells." (PMID 26657155, 2016). "Overexpression of GAB2 upregulated the secretion of several chemokines from ovarian cancer cells, including CXCL1, CXCL2 and CXCL8." (PMID 26657155, 2016). "Previous studies suggest that IKKβ regulates the expression of CXCL1, CXCL2 and CXCL8 in ovarian cancer cells." (PMID 26657155, 2016). "We found that overexpression of GAB2 in ovarian cancer cells upregulated expression of multiple chemokines, including CXCL1, CXCL2 and CXCL8 that exhibited mitogenic and pro-angiogenic activities." (PMID 26657155, 2016). "The underlying mechanisms likely involve the NFκB-regulated chemokine expression, since several studies have demonstrated that the expression of CCL2, CXCL1, CXCL2, and IL-8/CXCL8 is mediated by NFκB in ovarian cancer cells." (PMID 25790431, 2015). "The results revealed high expression of chemokines in the following ovarian cancer cell lines: CCL20 and 28, CXCL1, 2, 3 and 8 in OVCAR-3 cells; CCL28 and CXCL1 in SKOV-3 cells; CXCL1, 2 and 8 in CaOV-3 cells; and CXCL2 in TOV-21G cells." (PMID 23300534, 2012). "In syngeneic mouse models of ovarian cancer (OvCa), tumor expression of Egfl6 increased the intratumoral accumulation of polymorphonuclear (PMN) MDSCs and TAMs and their expression of immunosuppressive factors, including CXCL2, IL-10, and PD-L1." (PMID 39312740, 2024). "Moreover, in ovarian cancer, stromal cells, surrounding the tumor, release CXCL1, CXCL2 and CXCL8 exerting a chemoprotective role on cancer cells and contributing to polarize monocyte/macrophage toward an M2 tumor promoting phenotype." (PMID 33066172, 2020). "Indeed, we showed that inhibition of IKKβ not only significantly reduced expression of CXCL1, CXCL2 and CXCL8, but also suppressed clonogenic growth of ovarian cancer cells as a single agent." (PMID 26657155, 2016). "Together, these findings suggest that overexpression of GAB2 in ovarian cancers may contribute to upregulation of CXCL1, CXCL2 and CXCL8 expression in a context specific manner." (PMID 26657155, 2016). "We next determined whether CXCL1, CXCL2 and CXCL8 were required for proliferation and survival of ovarian cancer cells with GAB2 overexpression." (PMID 26657155, 2016). "Taken together, in consonance with previous observations, our results suggest that CXCL1, CXCL2 and CXCL8 could act as autocrine growth factors that directly promote proliferation and survival of ovarian cancer cells that overexpressed GAB2." (PMID 26657155, 2016). "In addition, CXCL1, CXCL2, and CXCL5 (ENA-78) can stimulate cell proliferation and migration in ovarian cancer." (PMID 26414070, 2015). "Finally, we observed that the DEGs DUSP5 (r = 0.487, p < 0.0001), CXCL2 (r = 0.355, p < 0.0001), and IL-6 (r = 0.401, p < 0.0001) were amongst some of the top correlative genes with AREG in the TCGA ovarian cancer cohort, adding a further degree of clinical relevance to our NanoString analysis." (PMID 38831884, 2024). "To examine whether high GAB2 levels in ovarian cancer cells are required for expression of CXCL1, CXCL2 and CXCL8, we suppressed GAB2 with inducible shRNAs in FUOV1 cells and observed that induced suppression of GAB2 decreased the mRNA levels of CXCL1, CXCL2 and CXCL8 compared with un-induced cells." (PMID 26657155, 2016).
atherosclerosis (24 papers, 2007 to 2026). A disease characterized by the build-up of fatty material and calcium deposition in the arterial wall resulting in partial or complete occlusion of the arterial lumen. "Atherosclerosis is caused by Sirt4 deficiency, which stimulates the NF-κB/IκB/CXCL2/3 pathway." (PMID 41567643, 2025). "CXCL-2 belongs to the cytokines involved in the pathogenesis of some cardiovascular diseases as acute myocardial infarction, atherosclerosis, obesity, diabetes, and ischemic stroke." (PMID 36769452, 2023). "There were six targets in the intersection with 137 candidate therapeutic targets of XFZYD, which included upregulated PTGS2, MMP9, and BCL2L1 and downregulated JUN, VEGFA, and CXCL2 in the atherosclerosis group." (PMID 33425996, 2020). "As shown by the gene correlation network, Cxcl2 and Il1b,43,44 2 important cytokines in atherosclerosis were included in the pink module." (PMID 30943771, 2019). "Since the combined blockade reduced atherosclerosis within the carotid artery, the site in which the fat transplant was located, our results suggest that the combined blockade of TNFα, CXCL2 and CCL2 reduced the ability of aged visceral fat to enhance atherosclerosis, at least locally." (PMID 36683460, 2023). "Meanwhile, Cxcl2 mediated the recruitment of neutrophils in the inflammatory response and is involved in the occurrence and development of many cardiovascular diseases, including atherosclerosis, ischemic stroke, and myocardial infarction." (PMID 33330655, 2020). "This activates M1-type macrophages which produce chemokines, namely CCL2, IL6, CXCL8, CXCL2, and CXCL20, leading to a complex cascade that encourages atherosclerosis." (PMID 39634983, 2024). "This was evidenced by a consistent macrophage phenotype characterized by significant upregulation of CXCL1, CXCL2, CXCL3, and IL-6, ultimately contributing to the promotion of accelerated atherosclerosis." (PMID 38162500, 2023). "These mice exhibited increased expression of several genes of the CXC chemokine gene cluster, including CXCL1, CXCL2, CXCL3, and Pf4, and classic proinflammatory cytokine genes such as IL-1ß and IL-6, which contribute to atherosclerosis." (PMID 38162500, 2023). "We found that the combined inhibition of TNFα, CXCL2 and CCL2 in recipients with aged fat transplants substantially reduced the degree of atherosclerosis at the carotid artery, aortic root and BCA." (PMID 36683460, 2023). "We next tested whether combined treatment with anti‐TNFα, anti‐CXCL2, and anti‐CCL2 would reduce the ability of aged fat transplants to enhance atherosclerosis." (PMID 36683460, 2023). "Based on experimental animal studies, the inhibition of chemoattractants such as CXCL2 and CXCL8 might lead to the resolution of inappropriate neutrophil mobilization and NETs induction, leading to the improvement of vasculitis and atherosclerosis." (PMID 34163363, 2021).
glioma (21 papers, 2017 to 2025). A benign or malignant brain and spinal cord tumor that arises from glial cells (astrocytes, oligodendrocytes, ependymal cells). "COX-2 knockout also downregulated proteins involved in tumor–macrophage crosstalk, including CXCL2 and E-selectin, with CXCL2 being a pro-angiogenic chemokine linked to glioma progression and a potential therapeutic target." (PMID 40649978, 2025). "We will further explore the specific mechanisms by which Fn upregulates cytokines such as CCL2, CXCL1, and CXCL2 to promote glioma development in future studies." (PMID 39660865, 2025). "The genes of the next chemokines, CXCL1,-2,-3,-5,-6,-8, have a very similar expression pattern, which includes a very restricted subpopulation of glioma cells, pericytes, and myeloid cells (among the latter, CXCL2,-3,-8 are highly expressed)." (PMID 39272976, 2024). "The binding of CXC-motif chemokine receptor 2 (CXCR2) by its ligand CXCL2 provides an alternative signaling pathway to induce angiogenesis in gliomas via activation of immune host cells and independently of VEGF signaling." (PMID 37626776, 2023). "In T98G, Hs683, and U373 glioma cells, the expression and secretion of CXCL2, CXCL3, and CXCL8 were measured after various temozolomide (TMZ) treatments." (PMID 35269652, 2022). "Even though variance between glioma samples was high (median: 11.6%, range: 2.05–15.6%), we detected a significant increase of CXCL2 expression." (PMID 33807899, 2021). "Overall, these results suggest that high levels of CXCL2 expression are important for glioma progression; however, the mechanism regulating MDSC recruitment requires clarification." (PMID 32391020, 2020). "Furthermore, the transient down-regulation of CXCL2 in oligodendroglioma cells significantly reduced their proliferation rate, and thus CXCL2 directly impacts glioma cell biology." (PMID 35269652, 2022). "Interestingly, the Bruyère group finds that the inhibition of chemokine C-X-C motif chemokine ligand 2 (CXCL2) expression in Hs683 glioma cells results in impaired cell proliferation." (PMID 34671362, 2021). "Together, these data suggested that Fn promoted glioma growth by increasing the levels of N-acetylneuraminic acid and the expression of CCL2, CXCL1, and CXCL2." (PMID 39660865, 2025). "We found Fn promotes glioma proliferation and upregulates CCL2, CXCL1, and CXCL2 levels in vivo and in vitro models of glioma." (PMID 39660865, 2025). "Neutrophils are recruited to glioma inflammatory regions by chemokines such as CXCL1, CXCL2, CXCL3, CXCL5, CXCL6, IL-8 (CXCL8), and IL-1β, which are secreted by glioma cells." (PMID 41272822, 2025). "Both in vivo and in vitro experiments demonstrated that Fn, as a key bacterium enriched in glioma tissue, promotes glioma proliferation and increases the expression of CCL2, CXCL1, and CXCL2." (PMID 39660865, 2025). "These tumors are lower grade glioma (in the case of CXCL3 and CXCL5) and diffuse large B-cell lymphoma (in the case of CXCL2 and CXCL3)." (PMID 37686093, 2023). "The exception was brain lower-grade glioma, where higher CXCL1 expression correlated with worse prognosis, while CXCL2 and CXCL5 expression correlated with better outcomes." (PMID 37686093, 2023). "There are many other proteins with pro-angiogenic activity currently under investigation in gliomas, such as the transmembrane protein vasorin, Ras homolog family member 1 (Rho1), and chemokine receptor 2 (CXCR2), along with its ligand CXCL2." (PMID 37626776, 2023). "In gliomas, the mechanisms underlying the spatial association of tumor CD73 and microglial CD39 are not certain and will require further study, though GSEA analysis of CD73hi tumor cells reveals elevated expression of chemokines such as CXCL2, which may recruit myeloid cells in cancer." (PMID 35973991, 2022). "The alternative proangiogenic factors CXCL2 and IL8, which act through CXCR2 or CXCR1, seem to be promising therapeutic targets due to their expression in glioma cell lines and mouse models." (PMID 33807899, 2021).
glioma (continued). "CXCL2 is expressed in several cell types present in GBM such us endothelial cells, glioma cells, T cells, mast cells and myeloid cells, and its expression level has been correlated with GBM aggressiveness." (PMID 34422657, 2021). "U87 glioma cells express several chemokines (CCL2, CCL20, CXCL1, CXCL2, CXCL8, etc.), among which IL-8 is the most abundant after radiation." (PMID 31488817, 2019). "In addition, both in vivo and in vitro models of glioma show that Fusobacterium nucleatum promotes glioma proliferation and upregulates CCL2, CXCL1, and CXCL2 levels." (PMID 39660865, 2025). "Another example of analysis is CXCL2 and CXCL5 in brain lower grade glioma." (PMID 37686093, 2023). "In gliomas with high CASZ1 expression, we found a restricted infiltration level but upregulated chemokines, including CXCL16, CCL22, CCL25, and CXCL2, which could attract DCs and T cells." (PMID 36276925, 2022). "While CXCL2, IL8 and their respective receptor CXCR2 seem to contribute to angiogenesis and tumorigenesis in GBM, there is also evidence suggesting an important role of those molecules in circumvention of anti-angiogenic therapy in gliomas." (PMID 33807899, 2021). "Furthermore, the median of CXCL2 expression was higher than the median of VEGF, implicating an extensive production of CXCL2 within glioma tissues." (PMID 33807899, 2021). "In addition to suppressing immunity, CXCL1 and CXCL2 also recruit myeloid cells to produce paracrine factors such as S100A9 and promote tumor cell survival found that silencing CXCL1 can down-regulate NF-κB and mesenchymal cell transformation, and inhibit the growth of human glioma xenograft." (PMID 34630121, 2021). "The original RNA-seq results suggested that glioma patients have higher levels of CCL20, CXCL1, CXCL2, CXCL5, and CXCL16 compared to noncancerous patients and that the levels of these small chemotactic cytokines in glioma are correlated with malignancy." (PMID 33483477, 2021). "The results showed that there were trends linking these cytokines, CCL20, CXCL1, CXCL2, CXCL5, and CXCL16, to ADO expression in gliomas but these correlations were not significant, probably due to the low number of patients recruited to the study." (PMID 33483477, 2021).
asthma (19 papers, 2014 to 2024). "With regard to CXCL2, little is known in asthma but it has been associated with a neutrophilic phenotype in mouse models." (PMID 32509795, 2020). "It is able to also enhance production of neutrophil recruitment associated chemokines like CXCL8 (in humans), CXCL1, CXCL2, CXCL3, CXCL5, and IL-1b, particularly in mold allergen-induced asthma murine models." (PMID 35386663, 2022). "This severe asthma cluster was associated with increased expression of CSF3, CXCL2 and CXCL8, genes usually associated with an “IL‐17 signature”,39 although it was evident that expression of these genes was heterogeneous across the cluster." (PMID 32096290, 2020). "There was an increased plasma expression of IL-10 and IL-6 in asthma and of c-x-c motif chemokine ligand 2 (CXCL2) and adrenomedullin (ADM) in pulmonary TB." (PMID 33023021, 2020). "Our previous reports also showed that ambient PM increases neutrophilic airway inflammation and production of inflammatory IL-6 and MIP-2/CXCL2 in a mouse model of asthma." (PMID 29882826, 2018). "Furthermore, CCL3 (MIP-1α) and CXCL2 (MIP-2) are important mediators in asthma and COPD because they are chemoattractant for monocytes/macrophages and neutrophils." (PMID 32509795, 2020). "Furthermore, CXCL2 was observed to be upregulated for which autocrine regulation of neutrophils had been demonstrated previously, offering potential to contribute to inflammation in asthma." (PMID 33076907, 2020). "Cxcl2 can also recruit Cxcr2+ endothelial progenitor cells into the lungs of allergen-sensitized mice and CXCL2-CXCR2 in asthma patients." (PMID 39768150, 2024). "While CXCL1, CXCL2, and CXCL5 gene transcripts were shown to be elevated in a mouse model of severe asthma, treatment with Ruxolitinib, an anti-inflammatory drug and powerful inhibitor of janus kinase 1/2 (JAK1/2), caused the upward spiraling to be reversed." (PMID 36164329, 2022). "Gene transcripts of some of these chemokines (CXCL1, CXCL2, and CXCL5) were found to be upregulated in a mouse model of severe asthma." (PMID 36164329, 2022). "In murine models of asthma, IL-17 stimulates and orchestrates airway neutrophilic infiltration by inducing the expression of neutrophil-attractant chemokines like CXCL1, CXCL2, IL-6, and IL-8 in humans." (PMID 35386663, 2022). "Intratracheal administration of S. commune in OVA-induced asthma model mice enhanced neutrophilic airway inflammation, increased the mRNA expression of CXCL1 and CXCL2 in the lungs, and provoked IL-17A, and IL-17F production in BAL fluid." (PMID 31852931, 2019). "They found that gene signature profiles of Th2 (IL-13, IL-4) and Th17 (CXCL1, CXCL2, CXCL3, IL-8, CSF3) immune responses were inversely correlated in these samples suggesting a reciprocal regulation of these two pathways in asthma." (PMID 26561853, 2015). "In addition, chemokines secreted by monocytes, e.g. CXCL2, or chemoattractants for monocytes, CCL4, were both elevated in CR, implying a plausible role of monocytes in the pathology of asthma." (PMID 30038057, 2018). "Taken into consideration the engagement in this process, in particular of mastocytes and their secretion of CXCL2, 4, 8, and other cytokines, there is no doubt regarding the etiopathogenic role of IL-33 in the development of asthma in response to various stimuli damaging bronchial epithelial cells." (PMID 31057533, 2019).
Arthritis (18 papers, 2012 to 2024). Inflammation of a joint. "Correlating the expression of Cxcl2 with the arthritis scores of the respective paws revealed that Cxcl2 expression in paws of arthritic M3R-deficient mice was already markedly enhanced in paws with low arthritis score." (PMID 26785775, 2016). "Interestingly, in M3R-deficient mice Cxcl2 expression was already markedly enhanced in paws with low arthritis score, while in WT mice only strongly arthritic paws revealed high expression of this chemokine." (PMID 26785775, 2016). "In WT mice, however, strong induction of Cxcl2 expression was only observed in paws with higher arthritis score." (PMID 26785775, 2016). "CXCL10 remained elevated throughout the response, whereas CCL2 and CXCL2 had decreased to control levels again by day 14 after arthritis induction." (PMID 22676339, 2012). "To further assess the severity of arthritis, we measured the mRNA levels of a variety of pro-inflammatory cytokines and chemokines, including Il18bp, Il18, Il1b, Il6, Il1r2, Ifng, Cxcl9, Cxcl1, and Cxcl2 in arthritic joints of IL-18BP KO and WT littermates." (PMID 37415987, 2023). "Our results also showed enhanced migration capacity of TIARP−/− neutrophils, which was mediated mainly through CXCL2, and that IL-6 signaling is critical for the recruitment of neutrophils into the arthritic joints after serum-transferred arthritis in TIARP−/− mice." (PMID 27995997, 2016). "This is in contrast to arthritis-susceptible B6 IL10−/− mice, where previously published data show that in addition to upregulation in IL-1β, IL-6, Cxcl1 and Cxcl2, IFNγ and Cxcl10 are upregulated 16-fold and 141-fold at 2 weeks, and 22-fold and 189-fold at 4 weeks, respectively." (PMID 24967703, 2014). "In the K/BxN serum-transfer arthritis model, activated neutrophils might express CXCL2 themselves." (PMID 31551776, 2019). "Changes occurring following castration that were independent of testosterone included BALF levels of TNF-α and CXCL2, lung levels of MMP-8, TIMP-1, and C5a, and lung autoantigen expression as well as lung cellular infiltrates and arthritis severity." (PMID 38086040, 2024). "AHR, CAV1, CRP, CXCL2, IRF1, SPP1 and other targets play important roles in the pathogenesis of arthritis and can be used as key targets for the treatment of arthritis." (PMID 37637408, 2023). "Triptolide, an effective component of TwHF, has been shown to reduce the levels of TNF-α, CXCL2, and VEGF in arthritis model." (PMID 38013265, 2023). "The role of neutrophils or monocytes in arthritis also needs to be tested, as the chemoattractant CXCL1 and CXCL2 were up-regulated in DNase II−/−STINGS365A/S365A mouse paws." (PMID 34901991, 2022). "All of the analyzed chemokines (CXCL2, CXCL10, and CCL2) peaked at 24 hours after arthritis induction." (PMID 22676339, 2012). "Other resolutive chemokines (RANTES/CCL5, MIP2/CXCL2, MDC/CCL22), and cytokines IL-1RA and IL-10 were quantified in SuperMApo and thus added to recombinant TGF-β (all in similar quantity than measured in SuperMApo) to treat arthritis." (PMID 30542342, 2018). "Treating the 5-mo-old DNase II−/−STINGS365A/S365A mice with anti–IL-6R reduced the arthritis score and the expression of IL-6 and MMP-3 but did not reduce the expression of TNF-α, CXCL1, and CXCL2." (PMID 34901991, 2022).